ZNF140 (zinc finger protein 140)
Description:
May be involved in transcriptional regulation as a repressor.
Synonyms: pHZ-39
Tractability: PROTAC: ubiquitination databases record sites on it.
Gene: Protein-coding gene on chromosome 12 (133,080,388 to 133,107,981, forward strand). Ensembl gene ENSG00000196387.
Subcellular location: Nucleus
Subcellular location (Human Protein Atlas): Nucleoplasm
Pathways (Reactome):
Gene expression (Transcription): Generic Transcription Pathway
Gene Ontology:
Molecular function: DNA-binding transcription repressor activity, RNA polymerase II-specific; protein binding; sequence-specific DNA binding; sequence-specific double-stranded DNA binding; DNA-binding transcription factor activity, RNA polymerase II-specific; RNA polymerase II cis-regulatory region sequence-specific DNA binding
Biological process: negative regulation of transcription by RNA polymerase II; regulation of transcription by RNA polymerase II; regulation of DNA-templated transcription
Cellular component: nucleus
Genetic constraint (gnomAD): Loss-of-function variants: 12 observed, 11.87 expected, observed/expected ratio (o/e) 1.01, 90% interval 0.65 to 1.62. The upper end of that interval is the gene's LOEUF score, 1.62, which puts it in group 6 of 6, group 1 being the genes least tolerant of losing a copy. Missense variants: 529 observed, 575.92 expected, observed/expected ratio (o/e) 0.92, 90% interval 0.86 to 0.99. Synonymous variants: 214 observed, 198.11 expected, observed/expected ratio (o/e) 1.08, 90% interval 0.96 to 1.21.
Homologues: Orthologues: chimpanzee ZNF140 (99% identical), macaque ZNF140 (98% identical), dog ZNF140 (89% identical), pig ZNF140 (88% identical). Paralogues in human: ZNF471 (52% identical), ZFP28 (51% identical), ZNF568 (50% identical), ZNF33B (50% identical), ZNF879 (50% identical), ZNF7 (50% identical), ZNF300 (49% identical), ZNF717 (49% identical), ZNF33A (49% identical), ZNF534 (49% identical), ZNF726 (49% identical), ZNF189 (48% identical), and 164 more.
Diseases named in the same sentence as ZNF140 in open-access papers:
ZNF140 is named in the same sentence as 1 disease in open-access papers, as found by Europe PMC text mining. Sharing a sentence is not in itself a finding about the gene and the disease.
ZNF140 shares sentences with these, for which no sentence is quoted: schizophrenia (1 paper).